NCMAP (non-compact myelin associated protein)
Description:
Plays a role in myelin formation.
Synonyms: MP11; C1orf130; FLJ42528
Tractability: Antibody: UniProt places it where antibodies can reach, with medium confidence; UniProt predicts a signal peptide or a membrane-spanning region; its Gene Ontology location is reachable by antibodies, with medium confidence.
Gene: Protein-coding gene on chromosome 1 (24,556,076 to 24,609,328, forward strand). Ensembl gene ENSG00000184454.
Subcellular location: Cell membrane
Gene Ontology:
Molecular function: structural constituent of myelin sheath
Biological process: peripheral nervous system myelin formation; positive regulation of myelination; regulation of myelination
Cellular component: paranode region of axon; plasma membrane; Schmidt-Lanterman incisure
Genetic constraint (gnomAD): Loss-of-function variants: 10 observed, 7.48 expected, observed/expected ratio (o/e) 1.34, 90% interval 0.81 to 1.89. That is too few expected variants to judge how well the gene tolerates losing a copy. Missense variants: 109 observed, 136.7 expected, observed/expected ratio (o/e) 0.8, 90% interval 0.68 to 0.94. Synonymous variants: 41 observed, 54.85 expected, observed/expected ratio (o/e) 0.75, 90% interval 0.58 to 0.97.
Homologues: Orthologues: macaque NCMAP (95% identical), guinea pig NCMAP (82% identical), mouse Ncmap (78% identical), chimpanzee NCMAP (77% identical), rat Ncmap (62% identical).